RNA5S13 (RNA, 5S ribosomal 13)
Synonyms: RN5S13
Gene: Ribosomal RNA gene on chromosome 1 (228,637,096 to 228,637,214, reverse strand). Ensembl gene ENSG00000202526.
Gene Ontology:
Molecular function: structural constituent of ribosome
Cellular component: ribosome
Homologues: Orthologues: dog 5S_rRNA (100% identical), guinea pig 5S_rRNA (100% identical), macaque 5S_rRNA (100% identical), mouse n-R5s108 (100% identical). Paralogues in human: RNA5S1 (100% identical), RNA5S10 (100% identical), RNA5S11 (100% identical), RNA5S12 (100% identical), RNA5S14 (100% identical), RNA5S15 (100% identical), RNA5S16 (100% identical), RNA5S17 (100% identical), RNA5S2 (100% identical), RNA5S3 (100% identical), RNA5S4 (100% identical), RNA5S5 (100% identical), and 26 more.